FN1 (fibronectin 1)
Diseases named in the same sentence as FN1 in open-access papers (continued):
Sharing a sentence is not in itself a finding about the gene and the disease.
lung carcinoma (59 papers, 2003 to 2026). "We discovered that many lncRNAs were located nearby important key regulators of lung cancer, including FN1, PCNA, BUB1, GNB1, and other cancer associated genes." (PMID 26918601, 2016). "Several recent studies have identified FN-1 mutations and polymorphisms that affect host susceptibility to a variety of diseases including calcium oxalate stone disease, schizophrenia, lung cancer, and fibrosing alveolitis in systemic sclerosis." (PMID 24886251, 2014). "We identified several CRC-associated proteins, e.g., FN1, HSPA8, and TLN1, in the blood plasma obtained from patients with lung cancer." (PMID 37241967, 2023). "In breast and lung cancer, FN1 activated the PI3K/Akt signal transduction pathway by binding to the integrin receptor α5β1." (PMID 33962392, 2021). "In this regard it has been showed that lung cancer cell adhesion to FN1 modulates the cetuximab-dependent cytotoxicity and radiosensitation by the synthesis and secretion of FN1 and the activation of p38 MAPK/ATF2 pathway." (PMID 33731188, 2021). "Here we show that blood platelets interact with lung cancer cells and that PD-L1 protein is transferred from tumor cells to platelets in a fibronectin 1, integrin α5β1 and GPIbα-dependent manner." (PMID 34853305, 2021). "In human lung cancer cells unfolded type III domain of FN1 inhibited TRAIL induced apoptosis through the activation of a PI3K/Akt/αvβ5 signaling pathway." (PMID 33731188, 2021). "Upon etoposide treatment, in the same lung cancer model FN1-β1 integrin signaling inhibits the chemotherapy-induced apoptosis due to a reduction of caspase 3 activity." (PMID 33731188, 2021). "The role of EMT biomarkers FN1 and VIM and the matric metalloproteinases, MMP-9 and MMP-7, in lung cancer in the background of ALK mutation is under study." (PMID 33091333, 2021). "FN1 overexpression stimulates cell growth and reduces apoptosis after treatment with standard chemotherapeutics in lung carcinoma." (PMID 30542512, 2018). "Indeed, blood platelets interact with lung cancer cells, and the PD-L1 protein is transferred from tumor cells to platelets in a fibronectin 1, integrin α5β1, and GPIbα-dependent manner." (PMID 39219215, 2024). "Moreover, in human lung cancer cells, the FN1 gene expression is suppressed by thiazolidinediones (TZDs), ligands of the peroxisome proliferator-activated receptors-γ (PPAR-γ), that dephosphorylate CREB and reduce the Sp1 nuclear protein expression." (PMID 33731188, 2021). "Finally, FN1 is such a complex component of the ECM which relies with important implications in cancer therapy resistance in particular in lung cancer." (PMID 33731188, 2021). "We identified at least five proteins of interest (NKX2-1, CAV1, YBX1, FN1 and CDH3) with two different machine learning models that may be associated with lung cancer patient survival." (PMID 33086649, 2020). "Moreover, according to the reported references, FN1 likely represented a signature biomarker for lung cancer in the prediction of responses to treatments." (PMID 33178362, 2020). "Then, the abnormal occurrence of RNA editing led to abnormal expression of oncogenes, such as, CTNNB1 and FN1, thus may be responsible for the lung cancer progression." (PMID 31158229, 2019). "Thus a combination of high hMENA11a and low stromal FN1 in the lung cancer tissues would predict a favorable outcome and the opposite would be true for high hMENAΔv6 and high FN1." (PMID 29907768, 2018). "Moreover, FN1 may play an important role in the pathogenesis of nasopharyngeal carcinoma and the drug resistance of lung cancer." (PMID 32697311, 2020). "In addition, oncogenes CTNNB1 and FN1 were highly edited and significantly overexpressed in malignantly transformed cell lines, thus may be responsible for the lung cancer progression." (PMID 31158229, 2019).
lung carcinoma (continued). "Further, co-culture experiments with lung cancer cells and human embryonic lung WI-38 cells showed increased expression of α-SMA, FN1, and VIM in WI-38 cells, along with significantly enhanced migration capacity." (PMID 40331946, 2025). "Different strategies have been pursued to target FN1 and its integrin receptors, as shown by the use of COX-2 inhibitors in models of tobacco-driven lung cancer." (PMID 33731188, 2021). "In this study, we found that alectinib and lorlatinib significantly reduced the expression of VIM, FN1, MMP-9, and MMP-7 and that finally inhibited the metastasis of lung cancer cells." (PMID 33091333, 2021). "Profiling the epithelial‐mesenchymal transition‐related molecular markers demonstrated decreased CDH1, TJP1, and OCLN and increased ZEB1, FN1, and EZH2 in response to CDKN2A silencing in lung cancer cells." (PMID 33155773, 2020). "Some ANXA5-regulated proteins such as FN1, ENO1, heat shock and Keratin family numbers are closely related to invasion and progression of lung cancer." (PMID 27684953, 2016). "Expression analysis reveals that hypoxia induced lung cancer related biomarkers, HIF and its modulating proteins (TGM2, CSNK1A1, CTNNA1, NAMPT/Visfatin, TNFRSF1A, ETS1, SRC-1, FN1, APLP2, DMBT1/SAG, AIB1 and AZIN1) are significantly down regulated." (PMID 23122428, 2012). "The levels of transmembrane protein 143, cadherin 5, fibronectin 1, and collectin-11 decreased significantly in the serum of patients with metastases compared with those of nonmetastatic lung cancer patients." (PMID 33728331, 2021). "Similarly, fusion between lung cancer cells and MSCs leads to enhanced metastasis through EMT, with downregulation of E-cadherin and upregulation of N-cadherin, vimentin, α-SMA, and fibronectin-1." (PMID 32632040, 2020). "The previous studies revealed that FN1 could stimulated the growth of non-small cell lung carcinoma cell via activating AKT signaling, and stimulated lung carcinoma cell growth via the phosphorylation of ERK." (PMID 26646797, 2016). "To examine whether the induction of EMT reduces HER2 expression, we analyzed mRNA expression of ERBB2, epithelial phenotype markers CDH1, EPCAM, MUC1 and OCLN, mesenchymal phenotype markers CDH2, FN1, SNAI2, and VIM in the A549 cell line (HER2-high human lung cancer epithelial cell line)." (PMID 34575017, 2021). "Together, these observations suggest that FN1, TLN1, ITGB3, HSPA8, and TUBA4A detection in the blood using SRM/SIS may serve as an indicator of tumors, and elevations in their concentrations coupled with PACSIN2 detection discriminate lung cancer from other malignancies." (PMID 34684727, 2021). "We also found several recurrent ALK fusions which have not been reported in lung cancer, but have been identified in other cancer types, such as VCL-ALK, FN1-ALK, and NPM1-ALK." (PMID 34508169, 2021).
pancreatic cancer (52 papers, 2011 to 2025). "Another report indicated that the high expression value of FN1 was associated with significantly poor survival in pancreatic cancer." (PMID 39218967, 2024). "Based on the expression levels of COL10A1/FAP/FN1, we further constructed a nomogram risk model for pancreatic cancer." (PMID 38063927, 2023). "From this risk model, we can see that the upregulation of COL10A1/FAP/FN1 expression is a risk factor for pancreatic cancer, and the upregulation of all three increases the risk of developing PC in patients." (PMID 38063927, 2023). "In pancreatic cancer, studies have found that FN1, encoding fibronectin, serves as a key signal transduction gene for therapeutic intervention in pancreatic cancer and can serve as a potential therapeutic and diagnostic biomarker for metastatic pancreatic tumors." (PMID 40678072, 2025). "Similarly, in pancreatic cancer, FN1 has been associated with tumor progression and resistance to therapy, indicating its potential as a therapeutic target." (PMID 38913913, 2024). "Based on this, we hypothesize that the upregulation of FN1 expression in PC may promote the progression of pancreatic cancer and is associated with a poorer prognosis for patients." (PMID 38063927, 2023). "In addition, for the first time, we highlighted the association between FN1 and cell viability, apoptosis and the cell cycle in pancreatic cancer cells." (PMID 34567847, 2021). "Furthermore, in pancreatic cancer, high expression of FN1 has been linked to poorer survival prognosis and it may serve as a key signaling gene for therapeutic intervention in pancreatic cancer." (PMID 38063927, 2023). "By neutralizing FN1 or inhibiting integrin receptors, the invasive capacity of pancreatic cancer cells was significantly reduced, with combined inhibition further decreasing invasiveness." (PMID 40678072, 2025). "Among them, pancreatic cancer cells in the cluster 8 with TIMP1+/FN1+ showed the strongest resistance, while the cluster 1 with CLDN18-/CEACAM5- and the cluster 7 with HSPA6+/NEAT1+ showed milder resistance." (PMID 38343537, 2024). "FN1 and ITGB1 not only play a role in pancreatic cancer, but also be closely associated with overall survival, immune cell infiltration, tumor mutation burden and microsatellite instability in pan-cancer." (PMID 35979350, 2022). "Thepredicted survival probability is much higher for pancreatic cancer patients with low mRNAexpression of FN1 or SERPINB5." (PMID 33884102, 2021). "In our study, the biological functions of FN1 in PDAC growth were validated in the pancreatic cancer cell lines PANC1 and SW1990." (PMID 34567847, 2021). "Amrutkar and colleagues demonstrated that FN1 secreted by stromal pancreatic stellate cells promotes gemcitabine resistance in pancreatic cancer cells by activating ERK1/2." (PMID 33731188, 2021). "The binding of FN1 to its receptors, typically cell surface integrins, trigger FN1 signaling pathways in pancreatic tumor cells, promoting tumor cell survival and chemoresistance, cell invasion, metastasis, and angiogenesis." (PMID 30736807, 2019). "In previous experimental studies, it was found that pancreatic cancer cells adhering to FN1 display increased cell proliferation and enhanced chemoresistance." (PMID 30736807, 2019). "It has been reported that EMT status was an important prognostic factor for pancreatic cancer and associated with portal vein invasion and lymph node metastasis, although this study utilized two EMT markers other than FN1." (PMID 30736807, 2019). "Other ECM proteins that were found, such as FN1 and Col1, have previously been reported to be involved in pancreatic cancer progression." (PMID 30923340, 2019). "The presence of both cellular and stromal FN1 and its interaction with integrins is necessary for pancreatic cancer progression, and inhibition of FN1 signaling was previously shown be an effective treatment strategy in vivo." (PMID 24708694, 2014).
pancreatic cancer (continued). "Additionally, increased FN1 expression in pancreatic cancer cells makes them resistant to gemcitabine through activation of the ERK1/2 pathway, protecting the cells from its proapoptotic effects." (PMID 40096084, 2025). "The metastasis of pancreatic cancer is associated with colon cancer protein 1 (MACC1), which positively interacts with SNAI1; this interaction represses CDH1 (which encodes E-cadherin) and enhances fibronectin 1 (FN1) expression, which promotes cell migration." (PMID 39941895, 2025). "Similarly, in a pancreatic cancer model, the deletion of Tregs resulted in decreased expression of Col and Fn1 mRNA in CAFs, accompanied by increased infiltration of effector CD4 + and CD8 + T cells." (PMID 38684596, 2024). "In COVID-19 infected patients, COL10A1/FAP/FN1 are also significantly upregulated, and FN1 may promote the progression of pancreatic cancer through the PI3K-AKT signaling pathway." (PMID 38063927, 2023). "Regarding the mechanism, knockdown of FN1 promotes cell apoptosis and induces cell cycle arrest by reducing the expression of cyclin D1, indicating that FN1 contributes to the development of pancreatic cancer by affecting cell apoptosis and the cell cycle in a certain manner." (PMID 34567847, 2021). "On the other hand, in pancreatic cancer plasma FN1 acts as a molecular switch, affecting the activity of the matricellular protein, SPARC and controlling whether SPARC promotes pancreatic cancer cell proliferation or induces cancer cell death." (PMID 33731188, 2021). "Given the sensitivity and reversibility of Fn1 expression in PDAC cells in TGF-β1 in vitro experiments, the detection of Fn1 expression may help the early detection of pancreatic cancer." (PMID 31375695, 2019). "Fibronectin (FN1) is the main constituent of the tumor stroma in pancreatic cancer." (PMID 30736807, 2019). "FN1 has been suggested as a prognostic biomarker for pancreatic cancer in a proteomics study." (PMID 29515771, 2018). "However, whether FN1 directly drives pancreatic cancer metastasis through the integrin-PI3K/AKT axis and whether it simultaneously participates in the remodeling of the immune microenvironment remain unanswered questions." (PMID 40678072, 2025). "The analysis lead to the identification of TIMP-1, FN-1, SPARC, IGFBP-3, LGALS3BP, and GREM1 as the most upregulated glycoproteins in early-stage pancreatic tumor tissues as compared to controls." (PMID 40345589, 2025). "We used miRNA transfection to generate a murine pancreatic cancer cell line that underexpresses FN1 by 2-fold, referred to as PANCO2 low FN1." (PMID 40096084, 2025). "The mechanism diagram further clarifies that FN1 activates the PI3K/AKT pathway by binding to integrin receptors, thereby promoting the invasion and metastasis of pancreatic cancer cells." (PMID 40678072, 2025). "We also identified FN1 and ITGB1 as core genes in the m7Gscore model, which affect immune cell infiltration and genomic instability not only in pancreatic cancer but also in pan-cancer." (PMID 35979350, 2022). "FN1 and ITGB1 can inhibit immune T cell activition by upregulation of macrophages and neutrophils, thereby leading to immune escape of pancreatic cancer cells and reducing the response rate of ICI treatment." (PMID 35979350, 2022). "Oncomine analysis of cancer vs. normal tissue confirmed that COL12A1, FN1, ITGA2, LAMB3, LAMC2, THBS2, and VCAN were significantly overexpressed in pancreatic cancer from different datasets." (PMID 34007003, 2021). "We further analyzed the overall survival of COL3A1, FN1 and ITGA2 in pancreatic cancer and normal tissues." (PMID 34461940, 2021). "Genes (n = 10) in cluster 2 were entirely labeled as activated stroma, containing periostin (POSTN), fibronectin 1 (FN1) and collagens (COL10A1, COL11A1), which have already been identified as deregulated in precursor lesions of pancreatic cancer." (PMID 29675033, 2018).
pancreatic cancer (continued). "Of these proteins, 21 proteins were identified exclusively in pancreatic cancer specimens including annexin 4A (ANXA4) and fibronectin (FN1)." (PMID 24708694, 2014). "In pancreatic cancer cells, ILF2 overexpression increases migration and invasion by regulating genes involved in epithelial-mesenchymal transition, such as upregulating vimentin (VIM) and fibronectin 1 (FN1) while downregulating cadherin 1 (CDH1/E-cadherin)." (PMID 39735599, 2024). "Therefore, we conclude that FN1 and ITGB1 can lead to immune evasion in pancreatic cancer and reduce the response rate of ICIs by up-regulating the activity of macrophages and neutrophils, and down-regulating expression of immune T cells." (PMID 35979350, 2022). "Several proteins with known roles in tumorigenesis such as FN1, TSPO, CD3E, and ZAP70 were present in the modules, which may be explored further as novel drug targets in pancreatic cancer." (PMID 36923555, 2022). "Finally, we concluded that FN1 and ITGB1 can also up-regulate macrophages and neutrophils and inhibit immune T cell activition in pancreatic cancer, leading to immune escape and reducing the response rate of ICIs treatment." (PMID 35979350, 2022). "Moreover, in the Pei pancreas dataset, COL12A1, FN1, ITGA2, LAMB3, LAMC2, THBS2, and VCAN mRNA expression levels were higher in pancreatic cancer tissue than in normal pancreatic tissue samples." (PMID 34007003, 2021). "In addition, the protein levels of COL3A1, FN1 and ITGA2 in pancreatic cancer were improved according to HPA." (PMID 34461940, 2021). "Interestingly, the proposed squamous subtype of pancreatic cancer exhibits high expression of FOSL1, TGFB2, SNAI2, and FN1, which is consistent with the FRA1:EMT phenotype we describe here." (PMID 27220889, 2016). "The innovation of this study lies in revealing the core role of the FN1-integrin-PI3K/AKT axis and proposing a combined therapeutic strategy targeting both the PI3K/AKT signaling pathway and integrins, providing a new avenue for overcoming therapeutic resistance in pancreatic cancer." (PMID 40678072, 2025). "In agreement with previous reports on pancreatic cancer exosomes, we observed that UM-derived exosomes triggered the transactivation of HHSCs, which produced α-SMA and increased amounts of extracellular matrix (ECM) proteins such as FN1, FN-EDA, and Col1A1 as compared with controls." (PMID 39272836, 2024). "Conversely, budesonide reduced the expression of the mesenchymal markers VIMENTIN and FIBRONECTIN (FN1) both in PDAC and PANC1 cells, providing molecular support to the hypothesis that budesonide induces epithelial features in pancreatic cancer cells." (PMID 38877560, 2024). "This was further corroborated in pancreatic cancer, where the c-MET inhibitor JNJ-38877605 did not prevent direct protein–protein interaction of MACC1 with the EMT-marker SNAI1, resulting in the upregulation of fibronectin 1 (FN1) and a repression of E-cadherin." (PMID 39580452, 2024).